PPARG (peroxisome proliferator activated receptor gamma)
Diseases named in the same sentence as PPARG in open-access papers (continued):
Sharing a sentence is not in itself a finding about the gene and the disease.
breast cancer (continued). "Interestingly, DHEA as well as DHA-5HT attenuated cytokine secretion by macrophages associated to breast cancer in a PPARγ dependent-manner." (PMID 32224850, 2020). "Though several significant associations of VDR, RXR and PPARγ to clinico-pathological variables were observed in sporadic breast cancer, there was only one significant correlation detected when VDR, RXR and PPARγ were correlated to clinico-pathological variables in BRCA1mut cases." (PMID 28427429, 2017). "Interestingly, PPARγ-deficient mice also show an increased occurrence of hormone-dependent mammary cancers." (PMID 25176219, 2014). "Experimental evidence in rodents has shown that overexpression of PPARγ is associated with an increased incidence and growth in mammary tumors, whereas knockdown of PPARγ expression was found to significantly inhibit spontaneous mammary tumor development." (PMID 23431460, 2013). "Breast cancer treatment andprevention may benefit from future studies of PPARγ therapy that address issues of susceptiblebreast cancer subtypes, duration and timing of intervention in the multistepprocess of mammary carcinogenesis." (PMID 19125177, 2008). "Notably, the genetic background could act as a strong modifier of the pro-tumor effect of PPARγ, as examplified by the predisposition of certain PPARγ polymorphisms (i.e., Pro12Ala and C161T) to breast cancer." (PMID 33946986, 2021). "Also PPARg physically associates with VDR in human breast cancer cells." (PMID 31141879, 2019). "Hence the current study aimed to investigate VDR, RXR and PPARγ in BRCA1mut breast cancer and to test whether any of the three may be associated with clinico-pathological criteria including overall survival." (PMID 28427429, 2017). "Moreover, PPARγ activation is associated with differentiation, proliferation inhibition of the normal and malignant cells and reversal of malignant phenotype of breast cancer cells." (PMID 26538209, 2015). "Thus, an explanation for the association of adiponectin with breast cancer is that functional reduction of PPARγ signalling, leading to reduced levels of BRCA1, may impair the DNA repair mechanisms." (PMID 22701472, 2012). "For example, CAV1, down-regulated in the cancer samples, was found to inhibit breast cancer growth and metastasis; the down-regulation of PPARG is associated with local recurrence and metastasis in breast cancer; and ANGPTL4 may act as a regulator of angiogenesis." (PMID 21060876, 2010). "It has also been shown that PPARG can indeed promote in vivo HER2-positive breast cancer proliferation." (PMID 40303293, 2025). "Stained with BODIPY 493/503, the findings demonstrate an elevation of fatty acid content in HER2-positive breast cancer cells following PPARG overexpression, whereas a decrease in fatty acid content is observed upon PPARG gene knockout." (PMID 40303293, 2025). "To investigate the impact of PPARG in HER2-positive breast cancer, we sequenced PPARG overexpressed and pCDH groups from SKBR3 and HCC1954 cell lines." (PMID 40303293, 2025). "As a result, PPARG emerges as a pivotal pro-carcinogenic factor in HER2-positive breast cancer, correlating with a poorer long-term prognosis and serving as a clinically significant biomarker." (PMID 40303293, 2025). "We classified HER2-positive breast cancer patients into two groups based on the median expression level of PPARG: high expression group and low expression group." (PMID 40303293, 2025). "HER2-positive breast cancer cells cultured with stable 13(S)-HODE concentration exhibited increased PPARG expression." (PMID 40303293, 2025). "Overexpression of PPARG was found to enhance the proliferation of HER2-positive breast cancer cells, while inhibition of PPARG resulted in inhibition of HER2-positive breast cancer cell proliferation." (PMID 40303293, 2025).
breast cancer (continued). "Molecular iodine (I2) induces cytotoxic effects in prostate cancer cell lines and antineoplastic effects in neuroblastoma and breast cancer through the indirect activation of PPARG." (PMID 40869121, 2025). "In vitro investigations have demonstrated a decelerated cell proliferation in HER2-positive breast cancer cells following knockdown of FASN following PPARG overexpression." (PMID 40303293, 2025). "Recent studies have highlighted PPARγ's potential role in cancer, particularly in colorectal and breast cancers." (PMID 40926269, 2025). "The primary focus of this research was to identify the peroxisome proliferator-activated receptor gamma (PPARG) as a contributing factor to decreased drug sensitivity by establishing anti-HER2 drug-resistant cell lines of HER2-positive breast cancer." (PMID 40303293, 2025). "We collected cell samples from four HER2-positive breast cancer cell lines to assess PPARG expression levels, which showed high levels of PPARG in JIMT1 cells and low levels in BT474 cells." (PMID 40303293, 2025). "We performed immunohistochemical staining on tissue samples from 193 HER2-positive breast cancer patients and classified them into low and high expression groups based on the color rendering results of the PPARG antibody." (PMID 40303293, 2025). "The results demonstrate that 13(S)-HODE can reduce the sensitivity of HER2-positive breast cancer to anti-HER2 therapy by targeting PPARG." (PMID 40303293, 2025). "Univariate COX regression analysis showed that in HER2-positive breast cancer patients, OS correlated with PPARG expression level, histological grade, tumor size, and lymph node metastasis status." (PMID 40303293, 2025). "PPARG has been determined as a promising biomarker of breast cancer following validation of its down-regulation in breast cancer and its connections to survival outcomes." (PMID 40604951, 2025). "In the multivariate analysis, both OS and DFS were independently influenced by lymph node metastasis status and PPARG expression level in HER2-positive breast cancer patients." (PMID 40303293, 2025). "Colony formation assays consistently confirm the role of PPARG in promoting the proliferation of HER2-positive breast cancer cells." (PMID 40303293, 2025). "In line with this, PPARγ levels have been reported to be significantly reduced in metastatic breast cancer tissues compared to primary tumours." (PMID 41373547, 2025). "INSR is activating PI3K, MAPK, and ERK signaling and has been linked to several tumors including leukemia and PPARG can bind to AP2-ɑ and SP1 and decrease the upregulation effect of AP2-ɑ on INSR in breast cancer." (PMID 41168841, 2025). "In hormone receptor-positive breast cancers, PPARγ activity generally restrains proliferation, whereas in aggressive triple-negative subtypes it supports metabolic reprogramming that fuels tumor survival and dissemination." (PMID 41476922, 2025). "In this context, we previously demonstrated that the conjugates of DHA and EPA with dopamine induced antiproliferative effects in MCF-7, SKBR3, and MDA-MB-231 breast cancer cells through activation of PPARγ, which upregulated expression of Beclin-1." (PMID 39863855, 2025). "We previously demonstrated that inhibiting the MEK-ERK pathway with a MEK inhibitor, in combination with a PPARγ agonist, facilitates the differentiation of breast cancer cells into adipocytes." (PMID 39273076, 2024). "PPARγ directly interacts with Nur77 and enhances its ubiquitination of Nur77 through the action of the ubiquitin ligase Trim13, thereby exacerbating breast cancer." (PMID 38933330, 2024). "The researchers then used the PPARγ agonist rosiglitazone (an anti-diabetic drug) in combination with the MEK inhibitor trametinib in a mouse breast cancer model and achieved differentiation of the breast cancer cells into adipocytes after EMT." (PMID 37935080, 2024).
breast cancer (continued). "The stimulation of apoptotic pathways in breast cancer cells has been connected to the activation of PPARγ, which helps to regulate the development of tumors." (PMID 39184716, 2024). "To date, it has been reported that the activation of PPARγ leads to inhibition of the development of melanoma, colon, lung, and breast cancer cells in vitro." (PMID 39000436, 2024). "Further evidence for n-3 PUFAs' potential as therapeutic agents comes from studies that demonstrate how they function as direct agonists for PPARγ in breast cancer cells." (PMID 39184716, 2024). "In luminal breast cancer patients, PPARγ is an independent predictor of longer survival, while the overexpression of pS6K1 is associated with poor prognosis." (PMID 39333940, 2024). "The binding of peroxisome proliferator‐activated receptor γ (PPARγ) to the orphan nuclear receptor Nur77 facilitates the ubiquitination and degradation of Nur77, and leads to aberrant fatty acid uptake for breast cancer progression." (PMID 38682467, 2024). "A PPARG regulon (containing 23 target genes) was associated with ICI response, and its function was validated by a colorectal cancer scRNA‐seq dataset, a breast cancer scRNA‐seq dataset, TCGA pan-cancer cohort, and 5 ICI transcriptomic cohorts." (PMID 38773508, 2024). "PPARγ was shown to act as a tumor suppressor promoting proliferation inhibition in colon and breast cancer." (PMID 39769169, 2024). "The interplay between PPARG and AKT1 is also evident in the context of cancer, with studies identifying their association in colorectal cancer, acute myeloid leukemia, and breast cancer." (PMID 38505269, 2024). "The inhibitory effects of PPARγ induce apoptosis, differentiation, and cell proliferation in breast cancer." (PMID 39765861, 2024). "This study demonstrates that MMPP is a dual-targeting drug for VEGFR2 and PPARγ, which stimulates apoptosis and restrains survival, migration, and invasion in breast cancer." (PMID 37942548, 2024). "In patients with breast cancer, PPARγ expression has a significant beneficial effect on recurrence-free survival." (PMID 38516703, 2024). "Utilizing murine breast cancer cells, we demonstrated a broad class effect of PPARγ agonists and MEK inhibitors in inducing cancer cell trans-differentiation into adipocytes." (PMID 39273076, 2024). "The PPARγ agonist mycophenolic acid can also reverse the malignancy of breast cancer cells by inducing their differentiation into adipocytes by activating PPARγ." (PMID 37935080, 2024). "One potential molecular mechanism for the prevention of mammary cancer has been suggested to be the stimulation of the peroxisome proliferator-activated receptor gamma (PPARγ) pathway." (PMID 38791595, 2024). "Binding of PPARγ to the VDR has been reported for human T47D breast cancer cells and PPARγ-mediated inhibition of VDR-mediated transactivation for T47D and LNCaP cells." (PMID 39273194, 2024). "Studies put in evidence that, in patients with breast cancer, high levels of PPARG are related to a major survival rate compared with those with lower expressions of this nuclear receptor." (PMID 37240821, 2023). "RXR- and PPARγ-forming heterodimers in breast cancer cells are reported to induce growth arrest and differentiation in breast cancer cells." (PMID 37509273, 2023). "In this system, PPARγ and its target genes were suppressed in the presence of CM from breast cancer cell lines compared to CM from HMECs." (PMID 37816052, 2023). "This same small molecular inhibitor was shown to inhibit growth of breast cancer cell lines through PPARγ-dependent pathways and was also suggested to impair MAPK signalling." (PMID 36510001, 2023). "Activated PPARγ enables ERBB2-positive breast cancer cells that produce high levels of fat to convert fatty acids into triglycerides, allowing these cells to avoid cell death caused by lipotoxicity." (PMID 37251321, 2023).
breast cancer (continued). "In breast cancer cells in vitro and in vivo, the activation of PPARγ induces cancer cells to differentiate into fat cells and induces apoptosis of fat cells through the upregulation of transcription factor C/Ebpβ, thereby inhibiting breast cancer cell growth." (PMID 37251321, 2023). "The antiproliferative effects of DHEA in MCF-7 breast cancer cells are mediated by the activation of the PPARγ, a nuclear receptor involved in several diseases, such as inflammation, metabolic disorders, cardiovascular disease, and different types of cancer." (PMID 37175104, 2023). "It has been reported that inhibition of the PPARG pathway reduces the aldehyde dehydrogenase positive population in ERBB2-positive breast cancer cells supporting its role in development of BC36." (PMID 37607964, 2023). "In breast cancer, the combination of PPARγ and RXR ligands has shown promise in inhibiting aromatase expression and estrogen-dependent carcinogenesis." (PMID 37645246, 2023). "After PPARγ was identified as a mature positive regulator of adipogenesis and lipid storage in 2013, inhibition of PPARγ was reported to reduce aldehyde dehydrogenase (ALDH) activity in ERBB2-positive breast cancer cells." (PMID 37251321, 2023). "Although the evidence about PPARγ in tumor cells has yielded opposing results, it is mostly reported to have a tumor suppressing effect in breast cancer cells." (PMID 36582446, 2023). "Our previous studies showed that DHEA induces anti-proliferative actions through the activation of the autophagy in estrogen receptor alpha-positive breast cancer cells in a peroxisome proliferator-activated receptor gamma (PPARγ) dependent manner." (PMID 36765778, 2023). "DHEA can exert antiproliferative effects in breast cancer cells not only through the activation of PPARγ but also by binding to the cannabinoid receptors (CBs)." (PMID 37175104, 2023). "In this experiment, CM from breast cancer cell lines suppressed PPARγ and its target genes FABP4 and CD36 in both ECs and pericytes compared to CM from HMECs." (PMID 37816052, 2023). "PPARg knockdown or treatment with PPARg antagonists has been shown to suppress hypermalignant subpopulations of breast cancer, liver cancer, prostate cancer and brain cancer." (PMID 36681687, 2023). "In particular, it has been documented that activation of PPARγ by agonists induced breast cancer cell death and inhibits breast cancer progression." (PMID 37175104, 2023). "In our cancer suppression review, we reported that PPARγ stimulates adipogenesis in colorectal and breast cancer cells, disrupting the YAP-Hippo signaling pathway, thereby forcing terminal differentiation and inhibiting the proliferation of cancer cells." (PMID 37251321, 2023). "PPARγ expression was significantly higher in brain metastatic lesions than in the primary tumors of breast cancer and melanoma patients." (PMID 35954274, 2022). "Previous studies have reported that the PPARγ-specific agonist RGZ had antitumor effects in breast cancer." (PMID 36611922, 2022). "On the one hand, on account of its proapoptotic and antiproliferative functions, PPARγ has been extensively considered a cancer suppressor, such as in colorectal cancer and breast cancer." (PMID 35690612, 2022). "Consistently, in the cohort of 308 patients with primary breast cancer, PPARγ was expressed in 58% of patients and its cytoplasmic expression was correlated with poor survival." (PMID 35922782, 2022). "Later, the downregulation of the chemokine receptor CXCR4 was further attributed to the metastasis-preventing effects of PPARγ in colon as well as in breast cancer." (PMID 35954274, 2022). "Peroxisome proliferator-activated receptor-gamma (PPAR-γ) is a nuclear hormone receptor superfamily transcription factor involved in metabolic functions as well as a suppressor of breast cancer tumors and was estimated to be down-regulated two-fold in tumors." (PMID 35388653, 2022).
breast cancer (continued). "With current data supporting that Camellia sinensis has a tumor suppressing effect on breast cancer cells, we wanted to elucidate a possible involvement of PPARγ." (PMID 35079875, 2022). "Our data suggest that higher PPARγ phosphorylation impairs immune cell infiltration in breast cancer, ultimately worsening patient outcomes." (PMID 36139700, 2022). "In our whole cohort of sporadic breast cancers, PPARγ expression in the cytoplasm of cancer cells was positively correlated with TIL levels and peritumoral inflammation." (PMID 36230483, 2022). "Previous studies have shown the capacity of PPARγ to inhibit epithelial to mesenchymal transition in breast cancer cells, having beneficial effects in reducing metastasis formation and reducing the proliferative capacity of tumor cells." (PMID 36142452, 2022). "In breast cancer and uterine leiomyomas, the growth-inhibiting effect of PPARγ activation was attributed to the inhibition of estrogen-receptor signaling." (PMID 35954274, 2022). "Mammary tumors were found to metastasize less upon PPARγ activation due to decreased MMP production." (PMID 35954274, 2022). "Clinical trials of RGZ early stage breast cancer patients have shown that PPARγ signaling is activated in breast cancer cells." (PMID 36114448, 2022). "These tumors were predominantly ER+ ductal breast cancers, further revealing the role of PPARγ in the development of ER+ breast cancer." (PMID 36611922, 2022). "Conformational changes in PPARγ induced by ligand activation provoked enhanced angiogenesis and faster tumor growth of mammary tumor cells." (PMID 35954274, 2022). "The crosstalk between the PPARγ and ERα signaling pathways revealed the important role of PPARγ in the development of ER+ breast cancer." (PMID 36611922, 2022). "Our study situates TRIB3 as an epigenetic regulator that controls the expression of PPARG in breast cancer cells." (PMID 36142452, 2022). "In this study, we demonstrate that TRIB3 regulates the expression of PPARγ, a transcription factor that has gained attention as a potential drug target in breast cancer for its antiproliferative actions." (PMID 36142452, 2022). "Subsequent reports of ligand-activated PPARγ inhibiting breast cancer development have experienced a rise." (PMID 36611922, 2022). "They demonstrated that the overexpression of PPARγ in breast cancer cells reduced tumor growth in a xenograft model and demonstrated increased autophagy in the tumor cells." (PMID 35954274, 2022). "The overexpression of PPARγ in breast tumors and the physiological effects of its ligands on breast cancer cells indicate that PPARγ will be a possible target in breast cancer clinical prevention and treatment." (PMID 36611922, 2022). "The report showed that GW7845 as an activator of PPARγ significantly inhibited nitrosomethylurea (NMU)-induced mammary tumor incidence, tumor number, and tumor weight in rats." (PMID 36611922, 2022). "In this report, we considered the NSAIDs to be agonists of PPARγ-induced PRODH/POX-dependent apoptosis in breast cancer MCF7 cells." (PMID 35163433, 2022). "In contrast, the expression of PPARG was significantly increased in breast cancer cells treated with Chidamide." (PMID 36425653, 2022). "In contrast, PPARγ can inhibit the PI3K/AKT pathway by upregulating PTEN transcription in breast cancer cells." (PMID 36276273, 2022). "recently showed that targeting the interaction between PPARγ and nuclear receptor Nur77 results in anti-cancer activity in several mouse models of breast cancer." (PMID 34984327, 2022). "In this report we found that NSAIDs (IND and DCF) as PPARγ agonists activate PRODH/POX-induced ROS-dependent intrinsic apoptosis in breast cancer MCF-7 cells." (PMID 35409177, 2022). "This is consistent with our results in clinical samples compared in the GEPIA database, where mRNA for PPARG was lowly expressed in breast cancer cells compared to normal individuals." (PMID 36425653, 2022).